RET (ret proto-oncogene)
Diseases named in the same sentence as RET in open-access papers (continued):
Sharing a sentence is not in itself a finding about the gene and the disease.
lung adenocarcinoma (continued). "Malignant pleural effusions (MPE) in lung adenocarcinoma frequently harbor RET rearrangements." (PMID 39882443, 2024). "Therefore, the final diagnosis was lung adenocarcinoma, RET fusion-positive, and the clinical stage was IVB (T4N3M1c)." (PMID 39882443, 2024). "In addition, histological transformation to SCLC has been described as an acquired resistance mechanism to pralsetinib in patients with RET-rearranged lung adenocarcinoma." (PMID 37627175, 2023). "Mutational profiling of 200 lung adenocarcinomas in Korean patients identified mutations of EGFR in 60.5%, KRAS in 12%, and translocations in anaplastic lymphoma kinase (ALK), c-ros oncogene 1 (ROS1), and RET proto-oncogene (RET) in 8.5% of cases." (PMID 35399416, 2022). "Moreover, the increased Src activation has been reported as a further mechanism of acquired resistance to different MKIs by activating RET downstream effector ERK1/2 in RET-rearranged lung adenocarcinoma." (PMID 33806299, 2021). "To gain insight into how RET fusions may activate growth, we used transcriptomic profiling of RET-driven lung adenocarcinomas, which highlighted an enhanced MYC signature in these tumors." (PMID 33318047, 2020). "Clinical studies in unselected NSCLC-patient populations conducted with RET TKIs did not demonstrate particular survival benefits; however, case reports described promising therapeutic responses to both vandetanib and cabozantinib in patients with RET-fusion-positive lung adenocarcinomas." (PMID 27150058, 2016). "The recent identification of RET fusions present in ~1% of lung adenocarcinoma patients has renewed interest in the identification and development of more selective RET inhibitors lacking the toxicities associated with the current treatments." (PMID 27429741, 2016). "We performed amplification refractory mutation system (ARMS) fluorescence quantitative PCR to detect the gene status of EGFR, ALK, ROS1 and RET in resected samples from 280 patients who were confirmed to have primary lung adenocarcinomas with N1-N2 lymph node metastasis." (PMID 27563816, 2016). "The KIF5B-RET fusion gene is capable of inducing the abnormal proliferation and differentiation of tumor cells through the constitutional overexpression and activation of the RET proto-oncogene, ultimately leading to lung adenocarcinomas." (PMID 26268359, 2015). "Structure of breakpoint junctions for ALK, ROS1, and RET reciprocal fusions in lung adenocarcinoma." (PMID 26437441, 2015). "Fusions of the tyrosine kinase genes ALK (anaplastic lymphoma kinase), ROS1 (c-ros oncogene 1), or RET (rearranged during transfection) occur in 1%–5% of lung adenocarcinomas (LADCs) and their products constitute therapeutic targets for kinase inhibitory drugs." (PMID 26437441, 2015). "Among these, RET fusion transcripts are detectable in about 1–2% of lung adenocarcinomas and might represent targets for therapeutic intervention with RET kinase inhibitors." (PMID 25884512, 2015). "However, efforts to target RET specifically with small molecule inhibitors such as Vandetanib or Cabozantinib in e.g. thyroid or lung adenocarcinoma have only shown limited success." (PMID 25749382, 2015). ", we could only confirm the existence of 3/270 (1.1%) the KIF5B/RET rearrangements in lung adenocarcinomas." (PMID 23342255, 2012). "Moreover, RET fusion-positive lung adenocarcinoma frequently metastasizes to the brain." (PMID 40496186, 2025). "Besides contrasting these findings using publicly available data, in this study we hypothesized that ROS1+ NSCLC is defined by specific transcriptomic signatures compared to other oncogene-driven tumors like ALK+ or RET+ lung adenocarcinomas." (PMID 39737401, 2024).
lung adenocarcinoma (continued). "In multivariate analysis adjusted for age, sex, smoking history, stage, surgical mode, and visceral pleural invasion, the CTNNB1 mutation and fusion genes (ALK, ROS1, RET) were negative prognostic factors for recurrence in early-stage lung adenocarcinoma (HR 4.47, p = 0.001; HR 2.73, p = 0.009)." (PMID 33140254, 2021). "To confirm the clinical relevance of this finding, we extracted 740 lung adenocarcinoma from TCGA database, among which 54 patients were confirmed with EGFR activating mutation (n = 25), FGFR1/2 amplification (n = 15), MET amplification (n = 12), or RET fusion (n = 2)." (PMID 31221965, 2019). "We hypothesize that carcinogens released by WSE produce frameshift truncations, resulting in loss of protein function in the tumor suppressors ATM and SMARCB1, and subsequent mutations in the oncogenes RET, KDR and EGFR exon 7 among others involved in the development of lung adenocarcinoma." (PMID 30093964, 2018). "A total of 1356 lung adenocarcinoma cases from April 2007 to May 2013 were sequenced for EGFR kinase domain mutations, KRAS mutations, HER2 kinase domain mutations, BRAF mutations, ALK fusions, ROS1 fusions, RET fusions and AKT1 mutations." (PMID 26486077, 2015). "Thus, we have successfully introduced FISH for diagnosing KIF5B/RET positive lung adenocarcinoma." (PMID 23342255, 2012). "During the study, 2343 patients with advanced lung adenocarcinoma were diagnosed, including 1167 EGFR+, 327 ALK+, 98 ROS1+, and 56 RET+ patients." (PMID 40751559, 2025). "The aim of this study is to detect fusion transcripts in the ALK, RET, ROS1, and NTRK1 genes through next‐generation RNA‐seq on samples obtained from paraffin‐embedded tissue, liquid biopsy, and EBC from 30 lung adenocarcinoma patients undergoing treatment." (PMID 39810398, 2025). "To complement the initial findings, we expanded the GSEA-based analysis to identify significantly upregulated or downregulated pathways in ROS1+ lung adenocarcinomas and cell lines in comparison to ALK/RET+ tumor samples." (PMID 39737401, 2024). "We found the first case of transformation of a RET-rearranged lung adenocarcinoma to SCLC after selpercatinib, a novel highly selective RET TKIs." (PMID 38057798, 2023). "Lung adenocarcinoma patient derived organoids were used to identify effective anti-cancer drugs poziotinib and pralsetinib for ERBB2 exon 20 insertions and RET fusions, respectively." (PMID 36568297, 2022). "In lung adenocarcinomas patients, EGFR mediates the activation of RET with neuroendocrine differentiation characterized by ASCL1 expression, implicating that EGFR is a key regulator of RET." (PMID 36147490, 2022). "Gene rearrangements that led to fusion RET proteins, on the other hand, were found in 20%-40% of PTC and 1%-2% of lung adenocarcinoma." (PMID 35582449, 2020). "The fusion gene of EML4-ALK was discovered in lung adenocarcinoma in 2007; since then, fusion alterations of ALK, RET, and ROS1 genes have been found in about 4–7% of patients with lung adenocarcinoma." (PMID 31083279, 2019). "On this study we describe a landscape of genomic alterations in lung adenocarcinoma patients with WSE in the tumor suppressors SMARCB1 and ATM, in addition to the oncogenes EGFR, RET and KDR." (PMID 30093964, 2018). "It was consistent with the previous research in lung adenocarcinomas, which found apatinib inhibits cellular invasion and migration by fusion kinase KIF5B-RET via suppressing RET/Src signaling pathway." (PMID 30400838, 2018). "In lung adenocarcinoma, fusions of ALK, RET, and ROS1 have been shown to be targetable genetic alterations." (PMID 28894699, 2017). "In lung adenocarcinoma, rearranged genes, including ALK, ROS1, RET, NTRK1, and NRG1, have been reported." (PMID 28894699, 2017). "RET rearrangement is the product from the fusion of RET gene and six partner genes, more frequent partners are KIF5B and CCDC6 observed in approximately 1–2% of lung adenocarcinoma." (PMID 27433281, 2016).
lung adenocarcinoma (continued). "Current international guidelines recommend analysis of the following seven genes before starting palliative intent therapy for lung adenocarcinoma: KRAS, EGFR, ALK, ROS1, HER2, BRAF, RET." (PMID 26018876, 2015). "This case highlights the therapeutic potential of pralsetinib in a patient with lung adenocarcinoma harboring a non-fusion intragenic RET deletion, representing a rare and understudied molecular subset of NSCLC." (PMID 40606448, 2025). "Here, we report the case of a middle-aged male patient with stage IV lung adenocarcinoma harboring a large RET intragenic deletion involving exons 2–11, without detectable RET gene fusion." (PMID 40606448, 2025). "In lung adenocarcinoma (LADC), RET fusions occur in ~0.35–0.88% of cases." (PMID 41465145, 2025). "As for the other reference genes such as ROS1, HER2, RET, MET, NTRK1, NTRK2, and NTRK3, our study did not identify mutations in these genes in patients with lung adenocarcinoma." (PMID 38828424, 2024). "In RET-rearranged tumors examples of these intracellular reactivated networks include RAS/MAPK signaling, which has been reported to confer resistance to MKI AD80 in RET-rearranged cell lines and to MKI ponatinib in preclinical patient-derived models of RET-fusion positive lung adenocarcinoma." (PMID 33806299, 2021). "For example, KRAS mutations are frequently detected in lung adenocarcinomas in smokers, whereas genetic alterations in EGFR, ALK, ROS1, and RET are frequently detected in lung adenocarcinomas in non-smokers." (PMID 28894699, 2017). "In this study, we evaluated the status of driver gene mutations in lung adenocarcinoma samples from 198 East Asian female never-smokers using the MassARRAY® LungCarta Panel and ALK, ROS1, and RET fusion assays." (PMID 25760072, 2015). "Prevalence rates of RET rearrangement in Asian populations have been reported at 1–2% for NSCLC and lung adenocarcinoma, and were estimated as high as approximately 6% in lung adenocarcinoma." (PMID 25881079, 2015). "To explore the role of XB130 in cancer cell cycle progression we conducted knockdown experiments using XB130 siRNA in human thyroid follicular carcinoma WRO cells (with RET-PTC rearrangement) and in human lung adenocarcinoma A549 cells (a cell line commonly used in lung cancer studies)." (PMID 22928011, 2012). "In addition, multiple gene fusions, such as NRG1, RET, and ALK, were only detected in IMA patients in our cohort and the detecting rate (16/51, 31.4%) of gene fusions was significantly higher than the unselected lung adenocarcinoma patients." (PMID 33505917, 2020). "Chimeric RET proteins generated by chromosomal rearrangements leading to RET fusion transcripts have been identified in ~1–2% of lung adenocarcinomas but might represent as many as 6–19% of tumors from never-smokers without other driver mutations." (PMID 25884512, 2015). "The RET fusion gene is a novel oncogene identified recently in NSCLC, and young Asian women, nonsmokers, and patients with lung adenocarcinoma are good candidates for personalized diagnosis and treatment." (PMID 36035311, 2022). "We discovered that 1% of lung adenocarcinomas from East Asian never-smoker female patients harbored gene rearrangements of ROS1 and RET, which have recently been recognized as driver genes in lung adenocarcinoma but had not been evaluated in East Asian female never-smokers." (PMID 25760072, 2015).
Hirschsprung disease (132 papers, 2002 to 2026). Hirschsprung disease (HSCR) is a congenital intestinal motility disorder that is characterized by signs of intestinal obstruction due to the presence of an aganglionic segment of variable extent in the terminal part of the colon. "Sharing this susceptibility gene, RET-associated MTC has a widely reported association with personal or family history of Hirschsprung’s disease." (PMID 39555152, 2025). "MEN2A RET mutations in exon 10 can be associated with Hirschsprung’s disease, a rare congenital intestinal motility disorder, due to the presence of an aganglionic segment in the terminal part of the colon." (PMID 39398337, 2024). "It is known that 10–25% of MEN 2A cases with the RET gene pathological variants in codons 609, 611, 618, or 620 co-occur with Hirschsprung disease." (PMID 38753051, 2024). "The linkage between a deficiency in RET and the onset of Hirschsprung’s disease is noteworthy, as RET plays a pivotal role in the development of Peyer’s patches." (PMID 37759758, 2023). "One of the major genes in this fate transition is RET, which harbors coding and regulatory pathogenic alleles (PAs) in ~50% of Hirschsprung disease (HSCR) cases." (PMID 37948459, 2023). "Hirschsprung’s disease is genetically linked, commonly associated with mutations in the RET proto-oncogene (RET) gene, which is crucial for enteric neurogenesis." (PMID 37759758, 2023). "In humans, inactivating mutations in the proto-oncogene RET are the most common known cause of Hirschsprung disease—a congenital condition defined by loss of enteric neurons in the distal gut." (PMID 36555308, 2022). "Accordingly, RET alterations are implicated in numerous disease phenotypes such as Hirschsprung’s disease and cancer." (PMID 35957881, 2022). "A large study identified an SNP in an intronic enhancer of RET that appeared to increase the penetrance of Hirschsprung disease in patients with rare RET/coding variants." (PMID 35983412, 2022). "Deletion of the RET gene or mutations in the exons and introns that result in changes in the intracellular and extracellular domains of RET lead to Hirschsprung's disease." (PMID 35434281, 2022). "Mutations of the RET gene have been identified in Hirschsprung’s disease (HSCR) and neuroendocrine tumors (NET)." (PMID 33958373, 2021). "Humans with mutations in the RET locus have Hirschsprung disease, and ARHGEF3 is located at the RET-dependent susceptibility locus identified at 3p21." (PMID 35174167, 2021). "RET gain of function variants is associated with multiple endocrine neoplasia, while heterozygous loss of function variants are the major risk gene for Hirschsprung disease." (PMID 34497401, 2021). "RET mutations causing Hirschsprung’s disease are usually loss-of-function mutations, present in 50% and 7–35% of hereditary and sporadic cases, respectively." (PMID 34949014, 2021). "V292M RET variant was described in germline of Vietnamese patients in cohort of 97 cases of Southern Chinese ancestry with Hirschsprung's disease." (PMID 32989896, 2020). "Mutations that lead to the constitutive activation of RET result in human multiple endocrine neoplasia (MEN) syndromes 2A and 2B, while mutation that inhibits RET activation can cause Hirschsprung disease (HSCR)." (PMID 32993133, 2020). "Mutations either activating or inhibiting RET result in several aggressive diseases, namely cancer and Hirschsprung disease." (PMID 32993133, 2020). "In some cases, mutations in RET C620, C618, C611 and C609, act as “Janus” mutations: that are able to induce both Hirschsprung’s disease and MTC in the same patient or in the same family." (PMID 31510104, 2019). "Many published studies have estimated the association of rs2435357 andrs1800858 polymorphisms in the proto-oncogene rearranged during transfection(RET) gene with Hirschsprung disease (HSCR) risk." (PMID 31644668, 2019).
Hirschsprung disease (continued). "Alterations in RET can result in gain or loss of function with RET loss of function resulting in conditions such as Hirschsprung’s disease." (PMID 31058838, 2019). "Hirschsprung’s disease is also associated with RET mutations but, in contrast to those associated with MTC, they are inactivating mutations." (PMID 31510104, 2019). "On the other hand, loss-of-function mutations throughout the RET extracellular region have been associated with Hirschsprung’s disease." (PMID 31535977, 2019). "In particular, mutations that reduce RET activity, which lead to Hirschsprung's disease, disturb the endosomal processing of RET that in the normal state regulates the duration and specificity of its signal." (PMID 28187001, 2017). "Isolated Hirschsprung disease can result from mutations in one of several genes, including the RET, EDNRB, and EDN3 genes." (PMID 28930629, 2017). "It is known that a loss of RET activation leads to Hirschsprung’s disease, whereas a gain in function leads to MTC." (PMID 27409604, 2016). "This has been supported by earlier extensive investigation of the RET gene locus for which a common variant within a RET enhancer was found to increase Hirschsprung disease susceptibility." (PMID 27628759, 2016). "We attempted to phase two variants that are 9 kb apart in the RET gene in a patient with Hirschsprung disease." (PMID 26883533, 2016). "RET mutations comprise the most common encountered in human Hirschsprung disease again suggesting that in a significant proportion of HSCR patients the recipient gut environment should be favourable for selected neural crest-derived stem cell transplantation." (PMID 25799576, 2015). "Although silent, the RET Ala45Ala allele (dbSNP ID rs1800858) was suggested to be either directly associated with or linked to another variant that conveys increased risk of Hirschsprung disease." (PMID 26102504, 2015). "A R114H mutation in the Ret proto-oncogene (RET) is known to be associated with Hirschsprung’s disease and shared by a small number of Chinese cases." (PMID 25956955, 2015). "Examples that have already been reported include a mutation in a RET enhancer that increases Hirschsprung disease risk as well as mutations that affect thalassemia, hemophilia, hypercholesterolemia, and pyruvate kinase deficiency." (PMID 25473435, 2014). "Mutations in the RET gene, associated with isolated Hirschsprung disease, are dominant loss-of-function mutations with incomplete penetrance and variable expressivity." (PMID 23820649, 2013). "The clinical relevance of RET was established when it was shown that germline mutations of the RET gene were responsible for two inherited human disorders, those being Hirschsprung's disease and MEN2a/b." (PMID 22355350, 2012). "Rare (RVs) and common variants of the RET gene contribute to Hirschsprung disease (HSCR; congenital aganglionosis)." (PMID 22174939, 2011). "Another mutation that decreases activity of an intronic enhancer in the RET gene and has been associated with some cases of Hirschsprung disease." (PMID 21871106, 2011). "Clinical features, RET gene sequence, enhancer genotype and dosage mutations in aCGH analysis of 18 Hirschsprung disease patients." (PMID 21712996, 2011). "RET is the major gene associated to Hirschsprung disease (HSCR) with differential contributions of its rare and common, coding and noncoding mutations to the multifactorial nature of this pathology." (PMID 21995290, 2011). "A similar situation exists for Hirschsprung disease, where hypomorphic mutations in both RET and endothelin can interact to cause the characteristic ENS deficits normally associated with heterozygous loss-of-function mutations in these genes." (PMID 19412548, 2009). "This disorder is similar to Hirschsprung disease, which is most often caused by mutations in the RET tyrosine kinase." (PMID 19412548, 2009).